IDO1 (indoleamine 2,3-dioxygenase 1)
Diseases named in the same sentence as IDO1 in open-access papers (continued):
Sharing a sentence is not in itself a finding about the gene and the disease.
non-small cell lung carcinoma (25 papers, 2015 to 2025). A group of at least three distinct histological types of lung cancer, including non-small cell squamous cell carcinoma, adenocarcinoma, and large cell carcinoma. "propose dual IDO1/TDO2 inhibition to enhance anti-tumor immunity in platinum-resistant non-small cell lung cancer." (PMID 38887298, 2024). "In tumors such as non-small cell lung cancer (NSCLC) and esophageal squamous cell cancer, higher IDO1 and TDO expression in kynurenine pathway is associated with higher TNM stage and shorter overall survival." (PMID 38218942, 2024). "When IDO1 activity is expressed as kynurenine to tryptophan ratio, higher IDO activity was associated with shorter PFS and OS in 26 patients with non-small-cell lung carcinoma (NSCLC) treated with nivolumab monotherapy." (PMID 38632994, 2024). "Clinically, smoker patients with non-small-cell lung cancer (NSCLC) exhibited high IDO1 levels and low Trp/kynurenine (Kyn) ratios." (PMID 36068203, 2022). "Here we examined IDO1 expression levels in non-small cell lung cancer (NSCLC) patients tumor/normal pairs underwent RT-PCR and comprehensive histological, immunohistochemica and clinical analysis." (PMID 28903363, 2017). "The expression and activity of IDO1 are increased in many cancers, and this is considered a negative prognostic indicator for esophageal and colorectal cancers, thyroid carcinoma, non-small cell lung cancer, and OSCC." (PMID 36831659, 2023). "To clarify the molecular mechanisms at the basis of IDO1 overexpression in multidrug resistant cells, we focused on the model of non small cell lung cancer A549 and A549/dx cells, where the difference of IDO1 expression between sensitive and resistant cells was particularly pronounced." (PMID 25955018, 2015). "Here we investigate IDO-1 expression in 2 cohorts of non-small-cell lung cancer (NSCLC) specimens, both in tumor cells and in immune infiltrate, with correlation of IDO-1 to PD-L1 expression, clinical patient demographics and outcomes." (PMID 40475772, 2025). "Moreover, individuals with non-small cell lung cancer who smoked had higher tumoral IDO1 levels and lower Trp/Kyn ratios compared patients who never smoked, further suggesting that smoking impacts KP activity." (PMID 37876966, 2023).
bladder cancer (24 papers, 2019 to 2025). "Additionally, indoleamine 2,3-dioxygenase 1 (IDO1) is highly expressed in bladder cancer and is linked to poor prognosis." (PMID 40869479, 2025). "Furthermore, we found an inverse association of IDO1 expression with miR-153 expression in 45 bladder cancer tissue samples." (PMID 31355138, 2019). "IDO1, its isoform, is overexpressed in bladder cancer, highlighting its potential as a therapeutic target." (PMID 40948378, 2025). "Suppressed expression of IDO1 resulted in decreased proliferation, migration, and invasiveness of bladder cancer cells." (PMID 36230984, 2022). "Metabolism of tryptophan is mediated by indoleamine 2,3-dioxygenase 1 (IDO1), which is downregulated by miR-153 in bladder cancer." (PMID 36158686, 2022). "IHC staining revealed that 63.2 percent of bladder cancer tissues had high levels of IDO1 expression, compared to 29.4 percent of the adjacent normal tissues." (PMID 35918736, 2022). "Indoleamine 2, 3-dioxygenase-1 (IDO1) is a promising target for immunotherapy in bladder cancer (BC)." (PMID 32907554, 2020). "In bladder cancer, it was found that indoleamine-2,3-dioxygenase-1 (IDO1) induces ZEB2 overexpression, which in turns increases the viability and proliferation of cancer cells." (PMID 32664703, 2020). "Our current study further demonstrated that miR-153's anti-tumor activity in bladder cancer cells was mediated by targeting IDO1, which in turn inactivated the IL6/STAT3/VEGF signaling pathway." (PMID 31355138, 2019). "miR-153 targeted IDO1 expression and inhibited bladder cancer cell tryptophan metabolism through inactivating the IL6/STAT3/VEGF signaling pathway." (PMID 31355138, 2019). "In conclusion, our current study demonstrates that miR-153 exerts its anti-tumor activity in bladder cancer by targeting IDO1 expression." (PMID 31355138, 2019). "At the gene level, miR-153 targeted IDO1 expression and inhibited bladder cancer cell tryptophan metabolism through inhibiting IL6/STAT3/VEGF signaling." (PMID 31355138, 2019). "We found that, IL-6 expression was significantly suppressed in the experimental groups compared to the control groups, while phosphorylated STAT3 and VEGF were also significantly decreased in miR-153-overexpressing or IDO1 knocked down bladder cancer cells." (PMID 31355138, 2019). "Similarly, in bladder cancer, IDO1 expression is related to cell migration ability, and silencing IDO1 reduces EMT through the IL‐6/STAT3/PD‐L1 pathway." (PMID 40103267, 2025). "IDO1 was found to be overexpressed in bladder cancer cell lines and tissues." (PMID 36230984, 2022). "On the contrary, miR-153 expression in bladder cancer cells could exert antitumor activity by targeting IDO1 3′-UTR and inhibiting cancer cell Trp metabolism subsequently." (PMID 35003126, 2021). "Furthermore, we found that IDO1 is a direct target of miR-153, which mediated miR-153 anti-tumor activity in bladder cancer via inactivating the IL6/STAT3/VEGF pathway." (PMID 31355138, 2019). "Indeed, our current data showed that high IDO1 expression promoted IL-6 secretion in bladder cancer cells." (PMID 31355138, 2019). "Thus, we speculate that the role of miR-153 in bladder cancer angiogenesis is to target IDO1 expression and regulate IL6/STAT3/VEGF signaling." (PMID 31355138, 2019). "The biosensor efficiency was confirmed by the determination of IDO-1 and IFN-γ in simultaneous measurements of the plasma and urine samples of patients diagnosed with bladder cancer and the control group." (PMID 40710094, 2025). "Despite clinical trials in bladder cancer have been initiated before, the newly initiated phase II trial (NCT04231864) is the first trial of IDO1 inhibitor in NPC." (PMID 33557876, 2021). "The constructed SPRi biosensor for IDO-1 and IFN-γ may have applications in regard to diagnosing bladder cancer using both urine and plasma samples from patients with this disease." (PMID 40710094, 2025).
bladder cancer (continued). "Furthermore, the expression of vimentin was found to be positively correlated with indoleamine 2,3-dioxygenase 1 (IDO-1), which exerts crucial regulatory functions on T-cell functions in bladder cancer." (PMID 36131933, 2022). "To further confirm the biological function of IDO1 in bladder cancer cells, we knocked down IDO1 expression in T24 and UMUC3 cells using si-IDO1 and found that si-IDO1 significantly reduced levels of IDO1 mRNA and protein in T24 and UMUC3 cells compared to the negative controls." (PMID 31355138, 2019). "To explore the underlying molecular mechanism of miR-153 in bladder cancer, we measured interleukin-6 (IL6) expression in supernatants of miR-153-overexpressing or IDO1 knocked down bladder cancer cells compared to the negative control cells." (PMID 31355138, 2019). "However, similar to human basal-like bladder cancer, murine tumors in our model displayed an upregulated expression of immunoinhibitory molecules such as CTLA-4, PD-L1 and IDO1 which can lead to cytotoxic resistance and tumor escape which was observed at 25 weeks." (PMID 31779626, 2019).
prostate carcinoma (24 papers, 2016 to 2025). A carcinoma that arises from epithelial cells of the prostate gland. "These conclusions also agree with our previous study that showed increased IDO1 and Tregs in PTEN-deficient prostate cancer tumor microenvironment." (PMID 36977733, 2023). "Our observation of the association of high IDO1 with poor overall survival in CCA patients is consistent with observations in colorectal, non-small-cell lung and prostate cancers." (PMID 34069452, 2021). "Enrichment for immune checkpoints including PD-L1, B7-H4, OX40L, and IDO-1 were identified in blastic prostate cancer, providing new therapeutic targets for patients with bone metastases." (PMID 31703602, 2019). "We used Mendelian Randomization to obtain unconfounded estimates of the association of IDO1 with ischemic heart disease (IHD), ischemic stroke and their risk factors, all-cancer, cancer of the prostate, lung and bronchus, and breast." (PMID 31186442, 2019). "Consistent with evolutionary biology, we also found IDO1 was also protective against prostate cancer." (PMID 31186442, 2019). "Interestingly, the IDO1 inhibitor lindrodostat had no inhibitory effects on LNCaP-EnzR or PC3 cells, which was consistent with the finding that prostate cancer cells expressed undetectable levels of IDO1 protein." (PMID 40759641, 2025). "However, we found IDO1 was protective against prostate cancer, which is rarely studied, although one study suggested it as a biomarker for prostate cancer." (PMID 31186442, 2019). "We also found IDO1 inversely associated with prostate cancer but not other cancers considered." (PMID 31186442, 2019). "Further supporting a role of inflammation-induced immune-suppression in the development of early-onset prostate cancer, we observed significant up-regulation of CTLA4 and IDO1/TDO2 pathways in tumors of the young cohort." (PMID 28027300, 2016). "Given that formyl-kynurenine was significantly upregulated by ADT, it is highly likely that ADT may induce IDO1 and/or TDO2 expression in prostate cancer (IDO2 has been reported to be expressed mainly in immune cells)." (PMID 40759641, 2025). "Additional sample sizes are required to confirm whether over-expression of IDO1 and/or CTLA4 in tumors may be predictive of prostate cancer recurrence in young men." (PMID 28027300, 2016). "Kolijn et al15 also proposed that IDO-1 regulates N-cadherin expression, which may prompt prostate cancer cells to produce IDO-1, but the authors did not evaluate PD-L1 and provided only mRNA and not protein data." (PMID 33692219, 2021).
Sepsis (23 papers, 2012 to 2026). Sepsis is defined as life-threatening organ dysfunction caused by a dysregulated host response to infection. "In the context of sepsis, increased IDO1 expression is believed to contribute to sepsis-associated immunosuppression, broadly affecting various immune cell populations, including T cells, B cells, monocytes, and neutrophils." (PMID 40715082, 2025). "The clinical studies clearly show that IDO1 and the activation of KP are associated with the course of sepsis and mortality prognosis." (PMID 36010680, 2022). "In animal models of sepsis, pharmacological or genetic depletion of IDO1 before LPS admission was associated with protection against LPS-induced septic shock at 24 or 48 h after sepsis induction." (PMID 36010680, 2022). "Sepsis-induced immune dysfunction/immunosuppression at the tolerant stage is closely associated with IDO1 activity." (PMID 31681271, 2019). "Clinical studies have shown an association of enhanced IDO1 activity in the early pro-inflammatory stage of sepsis with an increased disease severity and increased hypotension, which contributes to septic shock due to acute circulatory failure." (PMID 30279361, 2018). "During ongoing sepsis, there are indices that a prolonged elevated IDO1 activity increases the risk for poor outcome by provoking the maintenance of a protracted immunosuppressive phase, diminishing immune responsiveness and host defence." (PMID 30279361, 2018). "An enhanced indoleamine 2,3-dioxygenase 1 (IDO1) activity is associated with an increased mortality risk in sepsis patients." (PMID 30279361, 2018). "Notably, our findings revealed that Ido1 is the most prominently upregulated driver gene associated with ferroptosis in sepsis-associated ATI." (PMID 40715082, 2025). "Therefore, the inhibition of IDO1 before a scheduled surgery may reduce the risk for poor outcome associated with an enhanced IDO1 activity during sepsis." (PMID 30279361, 2018). "Research has demonstrated that IDO1 enhances the recruitment of neutrophils into the abdominal cavity of mice during bacterial peritonitis and sepsis induced by cecal ligation and perforation." (PMID 40597301, 2025). "We found that pediatric sepsis patients showed significantly elevated kynurenine (Kyn)/tryptophan (Trp) ratios, indicating increased indoleamine 2,3-dioxygenase 1 (IDO1) activity, along with higher Kyn levels compared to controls." (PMID 40715082, 2025). "To evaluate the direct impact of Kyn restriction on the recovery of sepsis-associated ATI, we inhibited Kyn synthesis by administering an IDO1 inhibitor, 1-methyltryptophan (1-MT)." (PMID 40715082, 2025). "HE staining and TEM imaging further revealed that IDO1 inhibition plays a crucial role in preserving thymic structural integrity and mitigating mitochondrial damage during early sepsis." (PMID 40715082, 2025). "ELISA analysis further revealed that sepsis induced a localized accumulation of Kyn in both the bloodstream and thymus, providing additional evidence of increased IDO1 activity." (PMID 40715082, 2025). "Plasma IDO1 activity gradually increased according to sepsis severity, and septic patients who died had higher IDO1 activity on admission than individuals who survived." (PMID 36010680, 2022). "So far, the role of IDO1 and the KP metabolites in sepsis and septic shock remains unresolved; therefore, in the below section of our review, we focused on exhibiting the available data on the topic." (PMID 36010680, 2022). "In the early stage of sepsis, the induction of IDO1 elicits powerful pro-inflammatory effects, which allows for fighting the invading pathogens." (PMID 36010680, 2022). "Inhibiting IDO1 activity prior to sepsis initiation has been reported to improve the outcomes of septic animals." (PMID 31681271, 2019). "Due to the fact that sepsis response quickly deletes tryptophan, our observations call attentions to the tryptophan restoration when designing IDO1 targeting-based clinical interventions of sepsis." (PMID 31681271, 2019).
Sepsis (continued). "IDO1-targeted therapies were proved to effectively protect septic animals from death by administration of IDO1 inhibitor 1-MT before sepsis initiation." (PMID 31681271, 2019). "Previous studies have shown that the blockade of IDO1 activity prior to sepsis induction either by gene specific knockout or by 1-MT inhibition increases survival rate of septic animals." (PMID 31681271, 2019). "Blockade of IDO1 activity prior to sepsis initiation by either gene knockout or IDO1 specific inhibitor 1-methyl-D-tryptophan (1-MT) reduces mortality of sepsis animals." (PMID 31681271, 2019). "In patients with sepsis, an increased IDO1 activity provokes systemic immunosuppression and is associated with an increased risk for mortality, when it is used as a prognostic indicator for probability of survival." (PMID 26881062, 2015). "Consequently, it is postulated that the excessive activation of the IDO1 in sepsis is a result of inflammatory processes, with the accumulation of Kyn being a pivotal element in the onset of ferroptosis." (PMID 40715082, 2025). "To determine whether ferroptosis influences IDO1/Kyn levels in thymocytes during sepsis, we measured IDO1 expression and Kyn production in CLP mice treated with the ferroptosis inhibitor Fer-1." (PMID 40715082, 2025). "To determine whether IDO1 activity and Kyn levels are elevated in pediatric sepsis patients, we measured plasma Kyn and Trp concentrations in sepsis patients and healthy controls." (PMID 40715082, 2025). "Notably, inhibition of IDO1 successfully restored thymic function and mitigated systemic inflammation during sepsis." (PMID 40715082, 2025). "Our findings reveal a novel role for the IDO1/Kyn/AhR pathway in ferroptosis, suggesting that targeting this pathway may offer a promising therapeutic strategy for sepsis." (PMID 40715082, 2025). "Targeting the IDO1/Kyn/AhR axis may provide a promising therapeutic strategy to restore T cell immunity and improve outcomes for patients with sepsis." (PMID 40715082, 2025). "In the early stage of sepsis, indoleamine 2,3-dioxygenase 1 (IDO1), a key enzyme that converts tryptophan to kynurenine, is activated and enhances proinflammatory effects that may result in severe tissue damage and septic shock." (PMID 36875476, 2023). "Thus, blockade of IDO1 in the model seemed to play a beneficial role in host protection during bacterial peritonitis and sepsis." (PMID 36010680, 2022). "The activation of the kynurenine pathway (KP) plays a dual role in sepsis—in the early stage, the induction of IDO1 elicits strong proinflammatory effects that may lead to tissue damage and septic shock." (PMID 36010680, 2022). "The IDO-1 gene was highly enhanced in the liver on day 5 after sepsis." (PMID 33946773, 2021). "Although primed MSCs on the control surface could not reduce IDO-1 expression, the injection of cells from the SF nanofibers significantly blocked IDO-1 induction by sepsis." (PMID 33946773, 2021). "To approach the clinical practice, we then tested if the inhibition of IDO1 after sepsis induction could also protect mice from sepsis death." (PMID 31681271, 2019). "The finding that IDO1 knockout mice are protected against lipopolysaccharide (LPS)-induced septic shock also supports the assumption that an enhanced endotoxin-induced activation of IDO1 provokes detrimental effects within conditions of sepsis." (PMID 30279361, 2018). "Mechanistically, our findings reveal that inflammatory signals upregulate IDO1 expression, which drives Kyn accumulation, leading to lipid oxidation-related gene transcription via activation of the AhR and ultimately resulting in thymocyte ferroptosis during sepsis." (PMID 40715082, 2025). "However, there remains limited understanding of IDO1’s regulatory role in thymocytes during sepsis." (PMID 40715082, 2025).
Sepsis (continued). "During the late phase of sepsis, dendritic cells (DCs) exhibit a tolerogenic/exhausted phenotype (low co-stimulatory molecules, high PD-L1/ICOS-L, secretion of IL-10, expression of IDO1)." (PMID 40806563, 2025). "We re-examined the response to ICI treatment in sepsis using PANscore and found that PD-1 was more expressed in the LowPANscore subgroup, while PD-L1, LAG3, TIGIT, TNFRSF9, CD40, IDO1 were expressed in the HighPANscore subgroup (P<0.05)." (PMID 38239341, 2023). "Patients with a poor outcome presented enhanced IDO1 activity and increased levels of KYN, KYNA, TGF-β and IL-6 in the early stage of sepsis, resulting in the development of endotoxin tolerance." (PMID 36010680, 2022). "The relationship between the pathophysiology of sepsis and Trp degradation enzymes, such as tryptophan 2,3-dioxygenase 2 (TDO2), Ido1 and Ido2, are reported." (PMID 30374077, 2018). "However, due to the lack of knowledge how IDO1 affects disease processes, no clinical trials of IDO1-targeted therapies of sepsis have been conducted yet." (PMID 31681271, 2019). "In contrast to the prevention, we demonstrated in this study IDO1 targeting alone failed to save septic animals if 1-MT was administrated after sepsis initiation, however, the combination of 1-MT and tryptophan supplementation significantly improved outcomes of animal sepsis." (PMID 31681271, 2019).